S100A9 (S100 calcium binding protein A9)
Diseases named in the same sentence as S100A9 in open-access papers (continued):
Sharing a sentence is not in itself a finding about the gene and the disease.
Sepsis (87 papers, 2010 to 2026). Sepsis is defined as life-threatening organ dysfunction caused by a dysregulated host response to infection. "Building on this theoretical framework, we assessed the predictive value of S100A9 for disease progression and mortality risk by evaluating its performance against commonly used clinical sepsis-related laboratory markers." (PMID 40478888, 2025). "Although we have validated the upregulation of NLRC4, TXN, and S100A9 expression in the peripheral blood of sepsis patients through qRT-PCR, there are still some deficiencies, such as limited number of enrolled patients and the lack of multicenter validation." (PMID 40028203, 2025). "In conclusion, S100A9, as an early inflammatory marker, has better predictive efficacy among common biomarkers associated with sepsis prognosis." (PMID 40478888, 2025). "MR analysis suggested that a decrease in GSTO1 levels is associated with an increased risk of sepsis, and that sepsis influences the levels of S100A9, TXN, and GSTO1." (PMID 40108736, 2025). "S100A9 is upregulated in sepsis patient’s blood sample and is associated with various complications of sepsis, including sepsis-induced acute liver injury, sepsis-induced myocardial dysfunction and lung damage." (PMID 40028203, 2025). "The constructs weretransfected into MDSCs isolated from S100A9-deficient miceundergoing late sepsis." (PMID 40458301, 2025). "Toconfirm S100A9 binding at the promoters of these cytokinegenes, we introduced S100A9 into MDSCs fromS100A9-deficient mice undergoing late sepsis response." (PMID 40458301, 2025). "This study also identifies S100A9 as a potential therapeutic target for treating sepsis-associated liver injury." (PMID 36768433, 2023). "It has been reported that patients with higher serum level of S100A9 are more susceptible to sepsis-related organ dysfunction." (PMID 36439140, 2022). "This gene and its partner S100A9 have been implicated in the development of MDSCs in cancer and sepsis, indicating a similarity between monocytic MDSCs and the MS1 cell state." (PMID 34103408, 2021). "In early sepsis (< day 5), the protein S100A9 was mostly confined to the cytosol, however, Hotairm1 causes a nuclear translocation of S100A9 in late sepsis, resulting in an immunosuppressive phenotype of Gr1+CD11b+MDSCs." (PMID 33807302, 2021). "We have shown that inhibition of S100A9 secretion and shuttling to the nucleus in Gr1+CD11b+ cells during late sepsis is associated with the development of MDSCs." (PMID 33335790, 2020). "Mechanistically, increased expression of Hotairm1 associates with its binding to and shuttling S100A9 protein from the cytosol to the nucleus in MDSCs after early sepsis response." (PMID 33335790, 2020). "PCR of cross-linked RNA extracted from S100A9 immunoprecipitates showed that Hotairm1 binds to S100A9 protein and transfers it from cytosol to nucleus in late sepsis Gr1+CD11b+ cells." (PMID 33335790, 2020). "In addition, we confirmed the predictive value of S100A9 as an independent risk factor for sepsis by multifactorial logistic regression analysis." (PMID 40478888, 2025). "Within this research, we explored the serum concentration of S100A9 during hospital admission, aiming to assess its role and reliability as a viable biomarker for identifying septic shock and predicting mortality risk in sepsis." (PMID 40478888, 2025). "Notably, ectopicexpression of S100A9 in MDSCs fromS100A9-deficient mice with late sepsis was sufficient to activateIL-10 or TGF-β promoter fused to the luciferase gene." (PMID 40458301, 2025). "Furthermore, S100A9 is more sensitive than lactate and IL-6 for assessing mortality risk in sepsis, while its specificity is basically equivalent to that of lactate and IL-6." (PMID 40478888, 2025).
Sepsis (continued). "Further multifactorial regression analyses, after controlling for the effects of other variables, conclusively identified APACHE II and S100A9 as independent influences in predicting the risk of death from sepsis, with both showing statistically significant (P < 0.001)." (PMID 40478888, 2025). "Cathepsin B (CatB), vascular cell adhesion protein 1 (VCAM-1), neutrophil gelatinase-associated lipocalin (NGAL), protein S100-A9, prosaposin, and thrombospondin-1 levels were significantly increased in the patients with sepsis compared with those of the controls (p < 0.001)." (PMID 39049003, 2024). "Thus, our data provide novel insights into the mechanism underlying sepsis-induced liver injury by linking S100A9 to AKT-AMPK-mitochondrial energy metabolism." (PMID 36768433, 2023). "In addition, a cohort study demonstrated that the level of S100A9 mRNA in the blood increased in the progression of sepsis, and its postponed upregulation was linked to the incidence of secondary hospital-acquired infections." (PMID 37197655, 2023). "Due to the embryonic lethality observed in S100A8-deficient mice and the lack of S100A8/A9 protein expression in S100A9-deficient mice, S100A9 knockout (KO) mice were used in this study to explore the role of S100A8/A9 in sepsis-induced pulmonary vascular hyperpermeability." (PMID 37978525, 2023). "In addition, the amount of Hotairm1 transcripts associated with the unphosphorylated S100A9 protein significantly decreased following Hotairm1 knockdown in late sepsis MDSCs." (PMID 39665047, 2023). "The results indicated an AUC of 0.799, suggesting that S100A9 could serve as a diagnostic marker for sepsis." (PMID 37978525, 2023). "Mice deficient in S100A9 fail to generate MDSCs and protracted sepsis." (PMID 35185915, 2022). "S100A9-deficient animals display pro-inflammatory characteristics in sepsis and pancreatitis." (PMID 36531717, 2022). "We found that MDSCs expansion decreases in S100A9-deficient mice during polymicrobial sepsis." (PMID 33335790, 2020). "Once the epithelial barrier is disrupted, ECs actively secrete damage-associated signals (i.e., S100A9) to prevent potentially pathogenic microorganisms from entering the systemic circulation, which can lead to severe infections, such as peritonitis or sepsis." (PMID 22962574, 2012). "In addition, S100A9 has good predictive efficacy for the risk of death in sepsis patients." (PMID 40478888, 2025). "Furthermore, deficiency in or blockade of S100A9, reduced organ damage during sepsis." (PMID 38094743, 2023). "The studies suggested S100A9 could be potential diagnostic biomarker of sepsis-induced AKI." (PMID 33863396, 2021). "A total of 1389 DEGs such as NOV, SEPT9, XIST, ESYT1 were upregulated in sepsis, whereas 1657 DEGs such as S100A9, IRAK3, MCEMP1, TLR5, CD177 were downregulated." (PMID 41542228, 2026). "The strong association of genes like S100A9 and KLHL3 with neutrophils, pivotal players in sepsis, suggests potential avenues for therapeutic targeting." (PMID 41542228, 2026). "FOXO1, KLHL3, and PCBP1 were weakly expressed in the sepsis group whereas MTF1, TMEM59, PIK3CB, and S100A9 were highly expressed in the sepsis group." (PMID 41542228, 2026). "We performed a ChIP assay using an anti-S100A9 antibodyand chromatin isolated from MDSCs from wild-type mice with late sepsis." (PMID 40458301, 2025). "In thecontext of MDSCs, we have previously demonstrated that MDSCs secrete copious amountsof S100A9 during the acute (early) phase of sepsis in mice." (PMID 40458301, 2025). "Recently, we reported that systemic short-term administration of the S100A9 inhibitor ABR-238901 in mice clearly attenuates sepsis-related cardiomyopathy, renal injury and liver injury 41-43." (PMID 40860162, 2025). "These pathways’ convergence emphasizes how crucial S100A8 and S100A9 are in coordinating the inflammatory response during sepsis." (PMID 41303672, 2025).
Sepsis (continued). "The study highlights the pivotal role of the S100A9 proteinin enhancing the immunosuppressive function of MDSCs during late sepsis." (PMID 40458301, 2025). "The machine learning algorithm screened three PCD-related genes, NLRC4, TXN and S100A9, as potential biomarkers for sepsis." (PMID 40028203, 2025). "Studies on mice with S100A9 deletion have shown that S100A9 has a protective effect against sepsis-induced heart damage, as seen by reduced mitochondrial dysfunction, apoptosis, and pro-inflammatory cytokine production." (PMID 40948795, 2025). "As sepsis enters a late phase response,MDSCs lose their ability to secrete S100A9, as it becomesdephosphorylated due to binding to Hotairm1 and moves from thecytosol to the nucleus." (PMID 40458301, 2025). "Furthermore, we explored whether combining S100A9 with conventional assessment tools could enhance diagnostic precision and prognostic accuracy, offering valuable insights to support early intervention and personalized treatment strategies for sepsis." (PMID 40478888, 2025). "S100A9 is a promising biomarker for diagnosing septic shock and forecasting clinical outcomes in patients with sepsis." (PMID 40478888, 2025). "S100A9 shows great potential as an indicator for diagnosing septic shock and predicting 28-day mortality outcomes in patients with sepsis." (PMID 40478888, 2025). "These outcomes imply that S100A9 functions as a potentially valuable biomarker for diagnosing septic shock and assessing the probability of death from sepsis." (PMID 40478888, 2025). "Then, four diagnostic genes of sepsis (LTF, MMP9, S100A9, and S100A8) and two diagnostic genes of relapsed B-ALL (LTF and MMP9) were screened by SVM-RFE, respectively." (PMID 41007866, 2025). "Serum S100A9 levels were higher within the sepsis cohort on admission in comparison to both control groups." (PMID 40478888, 2025). "In the training dataset, the expression of LILRA5, MGST1, PLBD1, and S100A9 was upregulated significantly in the sepsis group compared to the normal group." (PMID 40792106, 2025). "Based on three machine learning algorithms, we screened three potential biomarkers (NLRC4, S100A9 and TXN) and constructed a diagnostic model for sepsis." (PMID 40028203, 2025). "This suggests that elevated S100A9 levels can be used as a predictor of sepsis exacerbation, which, in combination with the APACHE II score, can provide valuable clinical information about the severity of the disease and prognosis." (PMID 40478888, 2025). "S100A9 was expressed in a variety of cell types, and was higher in NK cells from the sepsis group than in the control group." (PMID 40108736, 2025). "Through bioinformatics approaches, this study successfully identified five genes (IRAK3, S100A9, TXN, NFATC2, and GSTO1) associated with programmed cell death in the context of sepsis." (PMID 40108736, 2025). "Based on these cascade activations of inflammatory pathways involved in S100A9, and further constructing a mouse model of sepsis, it can be found that the initial S100A9 level in the sepsis model group was considerably higher than that in the baseline group." (PMID 40478888, 2025). "LILRA5, MGST1, PLBD1, and S100A9 were selected as hub genes and significantly upregulated in sepsis." (PMID 40792106, 2025). "It has also been proved that sepsis affects the levels of S100A9, TXN and GSTO1 from the perspective of genetics, but the underlying mechanism is still unclear and needs to be further verified by basic experiments." (PMID 40108736, 2025). "In conclusion, this research proposed three programmed cell death related genes (NLRC4, TXN, S100A9) as practical biomarkers for sepsis patients." (PMID 40028203, 2025). "We have previously shown that S100A9 protein movesfrom the cytosol to the nucleus in MDSCs during late sepsis in humans." (PMID 40458301, 2025). "Hotairm1 couples with theinflammatory protein S100A9 and shuttles it from the cytosol to thenucleus during late sepsis." (PMID 40458301, 2025).
Sepsis (continued). "In macrophages, the most differentially expressed genes after sepsis include S100a9, S100a8, Hbb-bs, Fth1, AW112010, Spic, Cxcl2, Cd14, Hmox1, and Vcam1." (PMID 38343542, 2024). "S100A9 has been proposed as a potential biomarker and therapeutic target due to its involvement in sepsis." (PMID 38245687, 2024). "Inhibition of S100a9 has been found to be effective in decreasing lung neutrophil infiltration and lung injury in mice with sepsis-related ARDS in a study of sepsis, and the same finding has been found in a model of myocardial infarction." (PMID 38745657, 2024). "Levels of Hotairm1 transcripts significantly increase in MDSCs in septic patients who develop late/protracted sepsis state, concurrent with an accumulation of unphosphorylated S100A9 protein in the nucleus." (PMID 39665047, 2023). "The findings revealed a significant increase in S100A9 plasma levels in individuals with sepsis (n = 81) compared with healthy controls (n = 22)." (PMID 37978525, 2023). "Hotairm1 RNA is detected in Gr1+CD11b+ cells at low levels during early sepsis, but it increases significantly during late sepsis, concurrently with the accumulation of unphosphorylated S100A9 protein in the nuclear compartment." (PMID 39665047, 2023). "First, the effect of S100A8/A9 on septic AKI needs to be clarified in S100A9 knockout mice and other animal models of sepsis." (PMID 37547329, 2023). "The inhibition of S100A9 phosphorylation in late sepsis Gr1+CD11b+ cells mirrored the significant increases in Hotairm1 binding to S100A9 protein, as demonstrated by the increase in Hotairm1 transcripts in the immunoprecipitated protein complex." (PMID 39665047, 2023). "Knockdown of Hotairm1 in MDSCs from mice and humans with late sepsis increases phospho-S100A9 protein." (PMID 39665047, 2023). "Among them, the AUCs of ITGAM, KIF1B, RRAGD, S100A9, SCOC, and SPTLC2 in the internal and external test sets were more than 0.6, indicating diagnostic significance for sepsis." (PMID 37834169, 2023). "Conversely, increasing Hotairm1 in early sepsis Gr1+CD11b+ cells by transfection decreases phospho-S100A9 protein levels." (PMID 39665047, 2023). "In conclusion, this study reveals the key role of S100A9 in promoting sepsis-induced hepatic dysfunction and injury, partially by activating AKT and inhibiting AMPK-mediated mitochondrial energy metabolism." (PMID 36768433, 2023). "Herein, our study confirmed the protective effect of S100A9 blockade on sepsis, as evidenced by alleviation of multiple organ injuries and decreased mortality rate in CLP mice receiving Paquinimod via oral gavage." (PMID 37337301, 2023). "Our results confirmed that S100A9 enhanced sepsis-mediated mitochondrial fission-fusion imbalance, ultimately resulting in excessive oxidative stress and epithelial cell apoptosis of kidney." (PMID 37547329, 2023). "It was noteworthy that S100A9 has been documented to modulate the activity of MDSCs in murine models of sepsis and lymphoma." (PMID 37337301, 2023). "Among them, S100A9 is a potential target for the treatment of sepsis, and further investigation is needed to determine if its khib is involved in sepsis progression." (PMID 37869005, 2023). "Conversely, the knockdown of Hotairm1 in late sepsis Gr1+CD11b+ MDSCs increased S100A9 protein phosphorylation." (PMID 39665047, 2023). "IL-10 promotes sepsis-induced immunosuppression and supports S100A9 protein translocation to the nucleus in mouse MDSCs during late sepsis." (PMID 39665047, 2023). "In contrast, in late sepsis Gr1+CD11b+ cells, S100A9 is present mainly in the nucleus in an unphosphorylated form." (PMID 39665047, 2023). "A bioinformatics analysis was performed with the help of public databases to determine if the S100A9 plasma levels were elevated in the circulation of patients with sepsis and its clinical value." (PMID 37978525, 2023).
Sepsis (continued). "We previously reported that in early sepsis Gr1+CD11b+ cells, S100A9 protein is mainly detected in the cytosol in a phosphorylated form (phosphorylated on threonine number 113)." (PMID 39665047, 2023). "Both phospho-S100A9 and phospho-p38 proteins were present in the same protein complex in early sepsis Gr1+CD11b+ cells and almost diminished during late sepsis." (PMID 39665047, 2023). "We found that depletion of Hotairm1 from late sepsis MDSCs from mice and humans restores levels of phospho-S100A9 protein." (PMID 39665047, 2023). "We found that levels of Hotairm1 transcripts are elevated in MDSCs from mice and humans with late sepsis, concurrent with the accumulation of S100A9 protein in the nucleus." (PMID 39665047, 2023). "During the acute phase of sepsis, the S100A9 proinflammatory protein resides in the cytosol in a phosphorylated form." (PMID 39665047, 2023). "In contrast, S100A9 relocalizes to the nucleus in an unphosphorylated form during the late/chronic sepsis state of immunometabolic paralysis." (PMID 39665047, 2023). "The present study shows that Hotairm1 prevents the phosphorylation of S100A9 protein in MDSCs in mice and humans with protracted sepsis." (PMID 39665047, 2023). "Real-time PCR analysis of the immunoprecipitated RNA showed Hotairm1 binding to S100A9 and phospho-S100A9 proteins at varying levels in Gr1+CD11b+ cells from mice with early sepsis." (PMID 39665047, 2023). "To examine the role of S100A9 in ALI in a mouse model of sepsis, we generated S100A9-knockout (KO) mice and subjected them to CLP." (PMID 36768433, 2023). "Protein-RNA co-immunoprecipitation and PCR, analysis of the immunoprecipitated RNA, showed low levels of Hotairm1 RNA binding to S100A9 protein in MDSCs from early septic patients, and the amount of Hotairm1 binding significantly increased during late sepsis." (PMID 39665047, 2023). "Accumulation of S100A9 protein in the unphosphorylated form in the nucleus in Gr1+CD11b+ cells during late sepsis reprograms them to the immunosuppressive Gr1+CD11b+ phenotype (i.e., MDSC)." (PMID 39665047, 2023). "To investigate the effect of S100A9 in septic AKI, we generated a sepsis-associated AKI model by CLP surgery." (PMID 37547329, 2023). "Several studies, including from our lab, have revealed that S100A9 is up-regulated in lung tissue in mice models of sepsis, and targeting S100A9 function attenuates sepsis-induced lung damage." (PMID 37978525, 2023). "Concomitantly, LSCM examination of monocytes showed marked enrichment of S100A9+ monocytes at late phase of sepsis." (PMID 37337301, 2023). "Western blot analysis of the bead-bound RNA-protein complexes showed increased S100A9 protein binding to Hotairm1 in late sepsis Gr1+CD11b+ cells." (PMID 39665047, 2023). "The research indicated that expression of S100A12 and S100A9 in the peripheral blood of sepsis patients was upregulated compared with that of healthy controls, which was consistent with our results." (PMID 37671148, 2023). "In contrast, S100A9 KO significantly attenuated CLP sepsis-induced reduction of occludin and VE-cadherin levels in the lungs (n = 6)." (PMID 37978525, 2023). "S100A9 protein expression increases in Gr1+CD11b+ myeloid cells during sepsis but accumulates in the nucleus in an unphosphorylated form as sepsis shifts to the late/protracted state." (PMID 39665047, 2023). "Increasing Hotairm1 transcripts in early sepsis Gr1+CD11b+ cells diminished S100A9 phosphorylation by p38 MAPK." (PMID 39665047, 2023). "In this paper, we identified a novel role of S100A9 on macrophages in facilitating sepsis-induced AKI and abnormal kidney function." (PMID 37547329, 2023). "Building upon these findings, the sepsis model of CLP in wildtype and S100A9 KO mice were used for subsequent experimentation, which closely simulated several clinical manifestations of human sepsis." (PMID 37978525, 2023).